ETS1 (ETS proto-oncogene 1, transcription factor)
Diseases named in the same sentence as ETS1 in open-access papers (continued):
Sharing a sentence is not in itself a finding about the gene and the disease.
tumor (continued). "Under pathological conditions, such as wound healing or tumor formation it has recently been shown that Ets-1 competitively inhibits the function of another Ets factor Fli-1 to promote the expression of CCN2, thereby promoting extracellular matrix deposition during cancer." (PMID 20454645, 2010). "Ets-1 is overexpressed in 44/55 (80%) of tumor tissues obtained from patients with ESCC." (PMID 20454645, 2010). "Similarly, in a pancreatic mouse cancer model of angiogenesis, the local administration of a dominant negative Ets-1 peptide using and adenoviral vector significantly blunted tumor growth and blood vessel density." (PMID 20454645, 2010). "Expression of Ets1 in tumor cells has been found to correlate with the grade of invasiveness." (PMID 19930697, 2009). "Together these results indicate that Ets1 may have an early role in cancer progression in addition to its more established role in tumor metastasis." (PMID 19142229, 2009). "Therefore, to better understand the nature of the ectopic clusters and investigate their possible tumor-like nature, we decided to analyse the impact of h-ets-1 expression on neural cells proliferation." (PMID 17987123, 2007). "In oral squamous cell cancers, Ets-1 was found in endothelial cells of well-vascularised tumours." (PMID 15365563, 2004). "Furthermore, ETS-1 may maintain the sustained growth and metastasis of tumor tissues by modulating the self-renewal and differentiation of cancer stem cells." (PMID 40181983, 2025). "In addition to their roles in tumor biology, the expression levels of ETS1, miR-203a-3p, and miR-204-3p may serve as prognostic indicators in PTC." (PMID 39941022, 2025). "Additionally, low-dose inhibition of STAT1/ETS1 combined with immune checkpoint blockade could synergistically enhance anti-tumor efficacy while minimizing adverse effects." (PMID 40948762, 2025). "Moreover, ETS-1 may interact with other transcription factors, such as Nuclear Factor Kappa B (NF-κB), modulating inflammation and the tumor microenvironment." (PMID 40181983, 2025). "Indeed, the binding of MALAT1 and ETS1 was reported in a recent tumor study." (PMID 40198713, 2025). "Although the ETS1 protein is normally found in the nucleus, it has also been found in the cytoplasm of endothelial cells during angiogenesis, including tumor vascularization, in the cytoplasm of tumor cells of various origins, and in the cytoplasm of tumor stromal fibroblasts." (PMID 39941022, 2025). "Therefore, targeting Ets1 improves antitumour effects of CTLs in multiple tumour types." (PMID 37968405, 2023). "However, the direct effects of ETS1 on function of tumor ECs remain poorly defined." (PMID 34867089, 2021). "Furthermore, we elucidated the action mechanisms of ETS1 as a tumor suppressor not only by directly activating down-stream targets linked with tumor cell proliferation/growth but also trans-activation of other tumor suppressor genes, such as ADAMTS9, TXNIP, STAT5A, and NOTCH1." (PMID 32477936, 2020). "Moreover, ETS1 can play a crucial role in tumor vasculature by modulating endothelial gene expression, so it raises the question of whether olaparib could somehow regulate VM in our model via promoting ETS1 activity." (PMID 33333852, 2020). "Interestingly, we found a distinct expression pattern of ETS1 depending on tumor types." (PMID 32477936, 2020).
tumor (continued). "Thus, the co-overexpression of lncRNA PAXIP1-AS1 and ETS1 could accelerate tumor development and silencing KIF14 suppressed tumor growth and angiogenesis." (PMID 31823805, 2019). "In addition, Ets-1 protein levels were significantly reduced in tumours from G9-treated mice." (PMID 28198367, 2017). "Therefore, tumor cell-derived ANGPTL2 may up-regulate ETS1-dependent activation of pro-angiogenic genes, promoting tumor angiogenesis." (PMID 25773070, 2015). "In addition, in vivo Ets1 expression increases 17β-estradiol-dependent tumor growth." (PMID 23874775, 2013). "Therefore, our results suggest that the inhibition of PARylation could be a novel therapeutic strategy for limiting cancer progression in Ets-1-expressing tumours." (PMID 23405229, 2013). "Because Ets1 regulates the expression of a large cohort of target genes that influence cellular proliferation and survival, Ets1 might play an important role in early stages of the carcinogenic process in addition to its better known role in tumor invasion and metastasis." (PMID 19142229, 2009). "Thus, the Ets1 oncogene may be important for oncogenic processes in both early and late stages of tumor development." (PMID 19142229, 2009). "Reported biomarkers exhibiting comparable dysregulation in both tumor and peritumor tissues include MDM2, E2F2, CDKN2A/p16, ETS-1, MGMT, and multiple microRNAs (e.g., miR-21, miR-96-5p, miR-145-5p)." (PMID 41683639, 2026). "We analyzed the mRNA expression levels of major proangiogenic molecules on the tumor surface and tumor depth, namely HIF1α, HIF2α, HIF3α, VEGF-A, VEGFR1, VEGFR2, and ETS-1." (PMID 41359448, 2026). "To address the challenges posed by tumour heterogeneity and reveal the expression patterns of EFNA4 and ETS1 in GC tissues, we performed reanalysis of single-cell RNA sequencing (scRNA-seq) data of GC samples." (PMID 41162582, 2025). "Therefore, in the carcinomas of epithelial origin, ETS1 might have a dual function; it may induce tumor vascularization and consequently provide oxygen and nutrition to cancer cells, and it may enhance invasion by the activation of ECM-degrading proteases in the cancer and/or in stromal cells." (PMID 39941022, 2025). "In tumour cells extracted from EGC and AGC scRNA-seq data, the expression of EFNA4 and ETS1 changed during pseudotime development." (PMID 41162582, 2025). "ETS1, a transcription factor involved in HIF-related pathways, likely reflects tumor-wide adaptations to hypoxia that manifest as a broader radiomic signature rather than being linked to specific texture patterns." (PMID 40500522, 2025). "Prognostic models for GC have been developed and tested based on the marker genes of tumour cell clusters or endothelial cells, EFNA4 and ETS1, and the former can better evaluate the prognosis of patients with GC." (PMID 41162582, 2025). "The expression of EFNA4 and ETS1 is depicted in the UMAP and violin plots, and ETS1 was significantly upregulated in tumour and endothelial cells." (PMID 41162582, 2025). "It has long been established that, in response to signals conveyed by ERK and c-Jun N-terminal kinase, Ets-1 binds to the promoters of matrix metalloproteinase (MMP) genes and activates their transcription in tumor cells." (PMID 41310821, 2025). "More importantly, the number of tumour cell sub-clusters was changed in AGC compared to that in EGC, and there seems to be some correlation between ETS1 and changes in tumour cells." (PMID 41162582, 2025). "In conclusion, miR-8485-mediated downregulation of UBN2, ETS1, MMS22L, GSK3B, and SLC44A1 inhibits tumor progression through mechanisms involving cell cycle arrest, metastasis inhibition, apoptosis induction, and choline metabolism." (PMID 40095604, 2025).
tumor (continued). "Importantly, ETS1 overexpression significantly increased the rate of tumor growth and markedly reduced overall survival in tumor-bearing mice, suggesting that ETS1 may promote immune evasion and tumor progression through suppression of anti-tumor T cell responses." (PMID 40777467, 2025). "Further, ETS-1 can inhibit transforming growth factor alpha (TGF-α) expression, thereby restoring tumor cell proliferation in vivo and promoting autonomous growth in culture." (PMID 40181983, 2025). "The expression patterns of ETS1 and EFNA4 in the AGC tumour cell subclusters were similar to those in the EGC tumour cell subclusters." (PMID 41162582, 2025). "ETS1 protein expression was determined in 54/57 PTC cases by IHC, as in 3 cases, due to the small size of the tumor (microcarcinoma), the PTC tissue was “spent” for FFPE slides to obtain a definitive diagnosis." (PMID 40722658, 2025). "In order to further identify the expression of EFNA4 and ETS1 during tumour cell differentiation, we analysed EGC and AGC tumour cells." (PMID 41162582, 2025). "ETS1, GSK3β, VEGFA, and YWHAZ were significantly upregulated in tumor tissues (p < 0.001), indicating their oncogenic roles in HNC progression." (PMID 39518147, 2024). "Cluster 0 expressed several tumour-related transcription factors such as ELK4, CREB1, cJun, JunD, KLF6, ETS-1 and ZNF217." (PMID 38480935, 2024). "ETS1 is a transcription factor and ETS1 gene expression correlates with AXL, IL6, and EFEMP1 in TNBC cell lines and tumor tissues." (PMID 38762181, 2024). "Our approach provided a significant number of genes related to T cell function in the tumor microenvironment, including HSP90AA1, ETS1, CXCR4, RGS1, and FYN, all detected at the gene level." (PMID 39548591, 2024). "CGP of PCL tissues revealed the tumor to be wildtype for CD79B, MYD88, CARD11, and TNFAIP3, with genomic alterations detected in SMO, CIITA, ETS1, HST1H1D, and SOCS1." (PMID 36342081, 2023). "Protein-coding genes with increased expression across all tumor types included E2F7, ETS1, EZH2, ID3/4, MKI67, PIK3R3, and TOP2A." (PMID 36865335, 2023). "Then the expression of ETS1 and ETS2 between tumor and normal samples was compared across 33 types of tumors included in the TCGA database." (PMID 36760475, 2023). "We found significantly positive Pearson R values for the majority of tumor entities, especially regarding correlations between FAP and the angiogenesis-related genes FLT1, KDR, HIF1A, and ETS1." (PMID 36672341, 2023). "Critically, using multiple datasets, we observe a positive correlation between ETS1 and TNS3 RNA levels in EWS tumor samples, suggesting that EWS tumor cells expressing ETS1 have the potential to exhibit a phenotype that promotes cell movement." (PMID 38187702, 2023). "Single-cell analysis dissected that ERRFI1, ETS1, NDRG1, and ZMAT3 were expressed in the tumor microenvironment." (PMID 37600707, 2023). "We further confirmed the p52-driven tumorigenic effects in vivo whereby TWEAK overexpression significantly increased the growth of U-87 MG tumour xenografts, but this was reduced by CRISPR/Cas9-mediated knockdown of NFKB2 or ETS1." (PMID 37087499, 2023). "Previous studies reported KLF2 promote cell proliferation and ETS1 and ETS2 contribute to angiogenesis, indicating tumor-promoting functions of these tumor-derived clusters." (PMID 37644609, 2023). "For HIF1A, ETS1, and VEGFR2, we detected significant protein levels in FAP-overexpressing tumor samples." (PMID 36672341, 2023). "In conclusion, we provide a novel view on the role of Ets1 as a proto-oncoprotein in the tumor process, which suggests that metastasis and colony formation in SW480 cells depend on the direct interaction between Ets1 and Sp1 instead of high Ets1 expression." (PMID 36305724, 2022).
tumor (continued). "Transcription factor E26 transformation specific sequence 1 (ETS-1) also binds with PXR and promotes PXR transactivation, thereby confers the sorafenib resistance in HCC tumor models." (PMID 35002522, 2022). "Then, we showed that CBX7 downregulated ETS1 to inactivate the tumor necrosis factor (TNF) signaling pathway, which inhibited tumor proliferation and enhanced the sensitivity of ccRCC cells to tyrosine kinase inhibitors (TKIs)." (PMID 35342353, 2022). "First, ETS1 expression was significantly higher in SHH‐α, SHH–β, SHH–γ tumor samples compared with SHH‐δ tumors." (PMID 33469989, 2021). "However, the role of Ets1 on tumor angiogenesis remains largely unknown." (PMID 34867089, 2021). "In NSCLC, the values of miR-365 are correlated with prognosis, and this is involved in tumor pathogenesis through its action on TTF1, ETS1, PTEN." (PMID 34199293, 2021). "ETS1 (ETS proto-oncogene 1, transcription factor) has initially been characterized as the proto-oncogenic transcription factor that contributes to tumor angiogenesis and invasiveness in cancer cells." (PMID 32477936, 2020). "As a result, consistent with their expression changes in tumor samples compared with adjacent samples, ENPP2 and ETS1 showed decreased expression levels in MDA-MB-231, a highly aggressive cell line, compared with MCF-7, a weakly aggressive cell line." (PMID 32412047, 2020). "Over-expression of Ets1/PEA3 into breast cancer cells expressing high levels of HER2/neu resulted in suppression of HER2 expression and prolonged survival with inhibited tumour growth in mice." (PMID 32225120, 2020). "Ectopic expression of ETS1 in MCF-7 cells significantly reduced cell proliferation in vitro and suppressed tumor growth in vivo." (PMID 32477936, 2020). "For example, unlike BRCA, high level of ETS1 was observed in cancer specimens from GBM, HNSC, KIRC, PCPG, SARC, and THCA; while other tumor types, including BRCA, showed low levels of ETS1 compared to normal specimens (data not shown)." (PMID 32477936, 2020). "In line with the data from our cell models, a residual tumor of an anaplastic PXA case operated during combination treatment of dabrafenib and the MEK-inhibitor trametinib had lost expression of ETS1, cyclin D1 and TERT." (PMID 31391125, 2019). "ETS1 was highly expressed in cisplatin-resistant OSCC cell lines as compared to that in the normal tissues; ETS1 was highly expressed in tumor tissues, suggesting that it is an important molecule in this process." (PMID 32038705, 2019). "Mechanistically, WTAP-mediated m6A modification led to the epigenetic silencing of ETS proto-oncogene 1 (ETS1), which was subsequently validated as a tumor suppressor in HCC, with the involvement of Hu-Antigen R (HuR) to stabilize ETS1 mRNA." (PMID 31438961, 2019). "Tumor miR-200b expression was significantly greater in LC-COPD than in LC patients, while that of its downstream markers ETS-1 and ZEB-2 was significantly reduced." (PMID 29371906, 2018). "These tumours also exhibited a decrease in KRAS, NAP1L1, and ETS1 expression in 786-O/miR-532-5p cells, as assessed by IHC." (PMID 30082686, 2018). "Consistently, we found that the tumor suppressor gene miR-125b in 1833 cells reduced WNT activity and targeted transcription factors, such as ETS1, HIF1 and WNT, likely affecting gene expression in bone metastasis." (PMID 29700305, 2018).
tumor (continued). "Strategies focused on down-regulating TMEM158, Mybl1, IL32, ETS1 and PTX3 should be considered to determine their effect on TNBC tumor progression." (PMID 28966727, 2017). "Usp9x, Ets-1 and NRAS protein expression was further assessed in a tissue microarray containing tumour and normal tissue." (PMID 28198367, 2017). "Vgll3 as a new partner of ets1 was unexpected and is very challenging as ets1 is also a proto-oncogene and VGLL3 has been proposed to play a role in tumor progression." (PMID 28870996, 2017). "A significant increase in the expression of ETS‐1 and HIF‐1α was found in the tumor sample from LPA‐treated of mice." (PMID 28236660, 2017). "Under the addition of DMSO, T24 Mut shETS1 and T24 Mut Double sh displayed a remarkable decrease in tumor volume, which suggested that the depletion of ETS1 (31.85%, P < 0.05) and both of GATA4 and ETS1 (41.16%, P < 0.05) inhibited the growth of T24 Mut cells." (PMID 26625313, 2016). "Suppression of ETS-1 by miR-144-3p was confirmed using luciferase assays; the effects of ETS-1 silencing were determined using a xenograft tumor model." (PMID 26826553, 2016). "Evaluating with Oncomine data, we found most target genes (BCL2, ERBB2/3, SIRT7, ETS1, Mcl-1, IL6R, and LIN28B) were significantly activated in HCC tumor tissues, consistent with miR-125b underexpression." (PMID 25861255, 2015). "In its tumor-suppressive functions, miR-125b has been reported to target ENPEP, CK2-α, CCNJ, MEGF9 or the proto-oncogene ETS1." (PMID 25633049, 2015). "Induction of Ets1 in solid tumors triggers neovascularization and the epithelial-mesenchymal transition (EMT) that drives tumor invasion." (PMID 25880398, 2015). "The protein profiles of nine targets, namely IGFBP2, IGF1, SHKBP1, ETS1, IL1α, STX2, MAML3, EGR3 and XIAP were verified as significant contributors to tumor classification." (PMID 24282616, 2013). "Through the basis of annotation suggesting that PTK2, CTTSL1, TNC, ETS1 and HSP90AA1 were involved in tumor cell proliferation, prevent tumor cell from apoptosis and promote tumor cell invasion in oral carcinogenesis." (PMID 23405089, 2013). "To determine if Ets1 expression also altered MCF7 growth characteristics in vivo, we assessed estrogen-dependent and -independent orthotopic tumor growth." (PMID 23874775, 2013). "Ets-1 is a potential transcription factor to IGF1R, and it is involved in tumour invasion and metastasis processes also regulated by syndecan-2 in HT-1080 cells." (PMID 22745764, 2012). "Ets-1 regulates the expression of many proteases of the MMP family, which accelerate tumor cell invasion and metastasis." (PMID 22971289, 2012). "Other evidences of the implication of IKKα in tumor promotion are that IKKα is induced by different proangiogenic agents such as TPA, UV radiation and Ets1 and that IKKα itself promotes angiogenesis and stimulates tumoral growth." (PMID 21755017, 2011). "However, it is important to note that Ets-1 also down-regulated genes encoding certain H2O2-detoxifying enzymes, suggesting that these cancer cells likely require and maintain a certain level of H2O2 to encourage the high growth rates inherent to tumour progression." (PMID 21042593, 2010). "We studied the expression of target genes encoding ICAM-1, PAI-1, MCP-1, and p16 to determine the potential roles of ETS-1 and ETS-2 in the development of this tumor." (PMID 18958307, 2008). "Phosphorylation of Ets sub-family members, Ets-1 and Ets-2, by MAPK-dependent pathways leads to persistent expression of tumour-related target genes including proteases such as uPA and MMPs." (PMID 17060941, 2006).